NRAS (NRAS proto-oncogene, GTPase)
Diseases named in the same sentence as NRAS in open-access papers (continued):
Sharing a sentence is not in itself a finding about the gene and the disease.
melanoma (continued). "Overall, our data are in agreement with literature data showing that BRAF is mutated in about 50% of melanomas and that NRAS is the second most frequently mutated gene." (PMID 30181807, 2018). "Silencing of CDK16 in both BRAF‐ and NRAS‐mutant melanoma cell lines led to cell cycle arrest associated with expression of p27 and reduced phosphorylation of the RB protein at S780." (PMID 29112787, 2018). "NRAS mutations are seen in all types of melanomas but seem to be slightly more numerous in melanomas of sun-damaged skin." (PMID 30360441, 2018). "We carried out droplet digital polymerase chain reaction to detect BRAF and NRAS mutations in plasma taken after surgery from 161 stage II/III high-risk melanoma patients enrolled in the AVAST-M adjuvant trial." (PMID 29112704, 2018). "In humans, of these family members, malignant melanomas predominantly bear NRAS mutations with only very rare KRAS and HRAS mutations." (PMID 30188888, 2018). "NRAS mutations are also found in melanoma, colorectal cancer, follicular thyroid cancer, and acute myeloid leukemia." (PMID 29682098, 2018). "One sample in the cohort expresses NRAS Q61K, an activating mutation commonly found in melanoma, thyroid, and colorectal cancers." (PMID 29441070, 2018). "The melanoma-driver mutations in NRAS and BRAF are mutually exclusive but the contribution of RAF signalling downstream of NRAS remains to be clarified." (PMID 28497782, 2017). "The CDK4 pathway comprising of signaling components like p16INK4a-cyclin D-CDK4/6-retinoblastoma is known to be altered in 90% of human melanomas, while 15–20% of melanoma cases show mutations in the NRAS gene." (PMID 29121869, 2017). "BRAF (V600E and V600K) and NRAS (Q61R and Q61L) mutations were detected in 65.9 and 6.8%, respectively, of the primary melanoma tumor biopsies." (PMID 28231855, 2017). "Sphere-forming assays demonstrated that KO of BIM also significantly protected the cells against the combination-induced disruption of spheres (P<0.05 or less) in both BRAF and NRAS mutated melanoma cell lines." (PMID 27086916, 2017). "Although targeted therapy has been tested for NRAS mutated melanoma, response rates still appear much weaker, than in BRAF mutated melanoma." (PMID 28522871, 2017). "TERT promoter mutations when combined with BRAF/NRAS mutations correlate with adverse outcome in adult melanoma." (PMID 28378855, 2017). "For example, mutations in KRAS are common in lung, colon, and pancreatic cancers, those in NRAS predominate in melanoma, and HRAS mutations are commonly seen in bladder, head and neck, and skin cancers." (PMID 29349077, 2017). "Results were similar in BRAF mutated (A375, HT144 and 451Lu), NRAS mutated (WM852c), and patient melanoma cells (MB2309 and MB2141)." (PMID 27086916, 2017). "Amplification and deletion of NRAS gene were rarely observed and were seen in both NRAS WT and NRAS mutated melanomas." (PMID 28668077, 2017). "Synergistic activity was seen with TAK-733 in combination with the pan-RAF inhibitor TAK-632 in both BRAF-mutated melanoma cells and NRAS-mutated melanoma cells with acquired resistance to BRAF inhibitors." (PMID 27650277, 2017). "Mutation of NRAS (particularly in codon Q61) occurs in around 15–20% of melanomas, with NRAS being considered an ‘undruggable target’, and thus an attractive candidate for synthetic lethal screening." (PMID 28097822, 2017). "In support of this idea, an increase in the expression of NOXA and BIM occurred upon treatment in both mutated BRAF and NRAS cell lines along with melanoma patient samples." (PMID 27086916, 2017). "Among these cases, we found NRAS Q61R mutation in 63.9% (46/72) of melanomas, NRAS Q61K in 25% (18/72), NRAS Q61L in 6.9% (5/72) and NRAS Q61H in 4.2% (3/72)." (PMID 28668077, 2017).
melanoma (continued). "Accordingly, we conducted this study to investigate NRAS Q61 mutations and M%NRAS in a series of 199 melanomas wild type for BRAF V600." (PMID 28668077, 2017). "To further elucidate the prognostic impact of mutations in the BRAF and NRAS genes, we analyzed the genotype of 217 patients with melanoma and retrospectively correlated the mutation status to primary tumor and clinical data." (PMID 28797232, 2017). "The analysis of 60 melanoma cell lines by Gast have revealed targeted focal amplifications of NRAS genes in 11% of them (n = 7/60) and amplification were detected in both NRAS mutated and NRAS WT melanomas." (PMID 28668077, 2017). "In contrast to BRAF mutated melanoma, the clinical and molecular characteristics of NRAS mutated melanoma subtypes are less well documented." (PMID 28522871, 2017). "Oral mucosal melanoma cells however show only infrequent mutations in either the NRAS or the BRAF molecular pathways that are common in melanoma of sun-exposed skin." (PMID 28638859, 2017). "The melanoma cells included BRAF or NRAS mutated cell lines and tumor samples from melanoma patients that have relapsed from current treatments." (PMID 27086916, 2017). "Patients with BRAF-mutant melanoma were significantly younger than those with NRAS mutations or WT patients (median 56 versus 66 and 67 years, respectively; p < 0.001)." (PMID 28797232, 2017). "To better understand the chromosomal mechanisms leading to M%NRAS increase, we compared M%NRAS and NRAS/chromosome 1 copy number status between 32 BRAF/NRAS WT and 57 NRAS Q61 mutated melanomas." (PMID 28668077, 2017). "Current literature however, suggests a more aggressive nature of NRAS mutated melanomas compared to BRAF mutated or wildtype melanomas." (PMID 28522871, 2017). "In a large-series study performed in the United States and Australia, when the NRAS mutation was present in melanoma, the tumor infiltrating lymphocyte grade was lower." (PMID 28107203, 2017). "In this study, we reported the prevalence of NRAS Q61 mutation and, for the first time, the variations of NRAS mutant alleles (M%NRAS), in a large series of human melanoma samples." (PMID 28668077, 2017). "The aggressive and fast growing behavior in animal models and the obtained phenotype in 3D culture reveal a perfect model for research in the field of NRAS mutated melanoma." (PMID 28522871, 2017). "The second most common mutation found in melanoma is affecting the NRAS proto-oncogene, GTPase (NRAS) gene with a frequency of ~20%." (PMID 28350340, 2017). "Herein, we present the clinical, biological and genetic characteristics of a peculiar melanogenic cell line - named MUG-Mel2, derived from a fresh biopsy tissue of a cutaneous metastasis of a highly aggressive NRAS p.Q61R mutated melanoma." (PMID 28522871, 2017). "Between 40–50% of human melanomas harbour activating mutations in BRAF, while approximately 15–20% of melanomas possess mutations in the NRAS gene." (PMID 28380427, 2017). "Currently, there has been remarkable progress in understanding melanoma pathogenesis, and numerous studies have now shown the correlation of BRAF and NRAS mutation status with clinical outcome and immune and targeted therapy strategies in melanoma." (PMID 29349077, 2017). "NRAS mutation was detected in 48 melanomas, corresponding to 18% (48/267) of all melanomas and 33.8% (48/142) of BRAF V600 wild type cases." (PMID 28668077, 2017). "Taken together, these data strongly supported that loss of BRAF and CRAF in NRAS-mutated murine melanoma cells induced resistances involving a compensatory effect of ARAF." (PMID 28497782, 2017). "NRAS-mutant tumors tended to behave more aggressively particularly in early stages of the disease in this high-risk melanoma population." (PMID 28797232, 2017). "The co-existence of TERT promoter mutations with BRAF or NRAS mutations (in 55% of cases) is associated with poor disease-free and melanoma-specific survival." (PMID 29108273, 2017).
melanoma (continued). "Taken together, these results indicated that when CRAF is knocked down in NRAS-mutated human melanoma cell lines, BRAF is able to compensate to maintain MAPK activation and proliferation." (PMID 28497782, 2017). "We have demonstrated that M%NRAS was highly heterogeneous; indeed, only 61% of NRAS mutated melanomas were heterozygous, while 30% of cases had a significantly increased M%NRAS (≥60%)." (PMID 28668077, 2017). "The mutational status of BRAF (exon 15) and NRAS (exon 2 and 3) was determined in melanoma samples of 217 patients with pyrosequencing and Sanger sequencing." (PMID 28797232, 2017). "The failure to stop disease progression altogether is likely to be due to the additional mutations seen in the melanoma over and above the NRAS driver mutation." (PMID 28253523, 2017). "KRAS mutations are extremely common in cancer of the pancreas, colon, and lung, while NRAS mutations predominate in melanoma and hematopoietic cancers." (PMID 28378457, 2017). "Characterization of M%NRAS were performed in a larger group of 104 NRAS Q61 mutated melanomas containing ≥80% tumor cells." (PMID 28668077, 2017). "By contrast, targeted treatment of patients with NRAS mutated melanomas is still a challenge, although an international phase 3 prospective study with the MEK inhibitor binimetinib recently provided promising results." (PMID 28668077, 2017). "A new drug application (NDA) application for binimetinib as monotherapy for NRAS-mutated melanoma was withdrawn finally from the FDA." (PMID 28954413, 2017). "This cooperative effect on cell proliferation was also observed in NRAS-mutated human melanoma cell lines." (PMID 28497782, 2017). "Histogram representation of NRAS Q61 mutant allele quantity (in percentage) in 85 ATGC NRAS mutated melanomas." (PMID 28668077, 2017). "Binimetinib was the first targeted therapy to show activity in patients with NRAS-mutated melanoma and offered a potential option for kinds of cancer with few effective treatments." (PMID 28954413, 2017). "NRAS encodes a small GTPase, which was the first protooncogene discovered in melanoma, and is found to be mutated in approximately 20% of cases." (PMID 28484715, 2017). "In keeping with published studies, there were frequent mutations of BRAF and NRAS in melanoma; BRAF, EGFR, KRAS, and STK11 in NSCLC; APC, BRAF, KRAS, and PIK3CA in CRC; KIT and PDGFR3A in GIST; and CTNNB1 in other tumours (desmoid fibromatosis)." (PMID 28196074, 2017). "Primary melanoma of the CNS in children is extremely rare, and usually linked to congenital melanocytic naevus syndrome, caused by mosaicism for oncogenic NRAS mutations." (PMID 28253523, 2017). "Targeted therapies with MAPK pathway kinase inhibitors (KIs) have been developed thanks to the discovery that BRAF and NRAS mutations are among the major oncogenic drivers of melanoma proliferation and survival." (PMID 28118616, 2017). "The most commonly activated pathway in melanoma is the mitogen‐activated protein kinase (MAPK) pathway, often constitutively activated through mutations in the V600 codon of BRAF (in 35–50% of melanomas) and the Q61 codon of NRAS (10–25%)." (PMID 28267273, 2017). "NRAS mutant melanomas rarely harbour either mutations in, or silencing of the negative regulator of the PI3K pathway, phosphatase and tensin homologue and exhibit lower levels of constitutive AKT signalling than those with BRAF mutations." (PMID 28497782, 2017). "For these reasons, the development of melanoma cell lines that retain comparable characteristics as in the in vivo state are crucial to search for novel treatment options in this particular subset of NRAS mutated melanomas." (PMID 28522871, 2017). "Then, a randomized phase III, open label, multicenter, two-arm study was designed to compare the efficacy of binimetinib versus dacarbazine in patients with advanced unresectable or metastatic NRAS mutation-positive melanoma (NCT01763164)." (PMID 28954413, 2017).
melanoma (continued). "NRAS mutations were more common in nodular melanoma than in superficial spreading melanoma (7/43 [16.3%] vs. 0/24 [0%], P=0.0367)." (PMID 28881731, 2017). "Current cancer therapies have focused on targeting driver mutations, including oncogenic BRAF and NRAS, which are frequent in melanomas." (PMID 28157711, 2017). "Other gene mutations in melanoma include NRAS, GNAQ and KIT, estimated to be present in 13–25%, 1.3% (but much more in uveal melanoma) and 2–8% (but more in acral/mucosal subtypes) of melanomas respectively." (PMID 29100459, 2017). "The five remaining melanomas all harbored MAPK pathway activating mutations in BRAF or NRAS and three had activating mutations in the β-catenin pathway." (PMID 28935960, 2017). "NRAS mutations are found in various malignancies including melanoma (20%), adenocarcinoma of the lung (1%), neuroblastoma (0.83%) and cutaneous T-cell lymphoma (4%)." (PMID 26821351, 2016). "This was supported by the presence of an NRAS mutation in both the CNS melanoma and in a more recent biopsy of the melanocytic nevus (c.182A > G (p.(Gln61Arg)))." (PMID 26769193, 2016). "Thirty-three tumors (23.6%) harboring BRAF mutations were identified as superficial spreading melanomas (SSM) compared with 26 (20.1%) melanomas with NRAS mutations." (PMID 27191502, 2016). "Again, in humans, it is epidermal melanocytes that develop into melanoma in response to NRAS or BRAF mutations." (PMID 27166257, 2016). "NRAS is the most frequently (about 20–30% of tumors) mutated isoform of the RAS family members in melanoma; very recently, an increase in NRAS mutant allele percentage during melanoma progression has been reported." (PMID 27833586, 2016). "Consistent with the importance of the Ras-Raf-MAPK pathway activation in melanoma, many somatic missense mutations in genes involved in or regulating this pathway including NRAS, BRAF, MAPKs, and RasGAPs have been identified." (PMID 26993606, 2016). "We asked if the double-mutated cell cultures consisted of two exclusive populations of cells (one with BRAF and another with NRAS mutations), or if both mutations were present in single melanoma cells." (PMID 27791198, 2016). "Whole genome sequencing analyses revealed that Tert promoter mutations are the most frequent mutations after BRAF and NRAS genes in melanomas." (PMID 26846696, 2016). "Common genes associated with aggressive melanoma include BRAF, with these mutations comprising the majority of melanoma cases (37–50%), followed by NRAS (13–25%) and NF1 (11.9%)." (PMID 27829238, 2016). "Oncogenic mutations in neuroblastoma RAS (NRAS), typically in codon 61, are observed in <∼20% of melanoma (2015)." (PMID 27608486, 2016). "Overall, these data suggest that melanomas from geographically different regions in NZ have markedly different mutation frequencies, in particular in the NRAS and EPHB6 genes, when compared to TCGA or other populations." (PMID 27191502, 2016). "In an inducible NRAS Q61K genetically engineered mouse model of melanoma, the combination of MEK and CDK4/6 inhibitors caused tumor regression that paralleled extinction of mutant NRAS, but either monotherapy alone did not." (PMID 27167191, 2016). "The co-detected additional mutations identified using the Melacarta Sequenom panel included six melanomas containing NRAS together with EPHB6G404S mutation, and six melanomas containing NRAS together with METT992I mutation." (PMID 27191502, 2016). "Further study is required to determine the role of RASA1 in melanomas with oncogenic NRAS mutations, especially in metastasis, and the effect of RASA1 on R-Ras activation in melanomas that are wild-type for BRAF and NRAS." (PMID 26993606, 2016). "In contrast, NRAS mutations were more common in melanomas arising from the arm/leg extremities (45.2%) compared with BRAF mutant (30.0%) or melanomas without mutations detected (33.7%) for this location." (PMID 27191502, 2016).
melanoma (continued). "Mutations in HRAS are most frequently found in melanoma, bladder and mammary carcinoma; NRAS mutations are found in melanoma and thyroid carcinoma; and KRAS mutations are most prevalent in cancers of the bladder, ovary, thyroid, lung, colon and pancreas." (PMID 27096871, 2016). "Understanding the reasons for variable mutation frequency will lead to precise interventions to effectively target oncogenic mutations, such as in NRAS or EPHB6 in melanoma." (PMID 27191502, 2016). "In this study we found that NRAS mutations were associated with nodular melanomas, which on average had a higher Breslow thickness than other melanoma types." (PMID 27191502, 2016). "The pharmacological effects of BRAF and MEK inhibitors were similar between PDX-derived histocultures and their corresponding PDX, on 2 models of BRAF and NRAS-mutated melanomas." (PMID 26909610, 2016). "Activating mutations of NRAS are presented in three of 77 cases and c-kit appears absent in canine mucosal melanomas, in contrast to human mucosal melanoma, where these genes are mutated in 4% and 14% of tumors, respectively." (PMID 29056717, 2016). "Several studies have shown that over-expression of EGFR, FGFR3, PDGFRβ, CRAF, and NRAS in melanoma have been associated with BRAFi resistance." (PMID 27448964, 2016). "A concomitant AURKA/BRAF and AURKA/MEK targeting overcame MAPK signaling activation-associated resistance signature in BRAF- and NRAS-mutated melanomas, respectively, and elicited heightened anti-proliferative activity and apoptotic cell death." (PMID 26962685, 2016). "To determine the frequency of double mutations in early passage cultures in general in a larger patient cohort, we Sanger sequenced the NRAS locus in all BRAF-mutated cell cultures generated from 2013—2015 archived in our melanoma biobank." (PMID 27791198, 2016). "Although mutations in KRAS (2%) and HRAS (1%) have been observed in melanoma specimens, NRAS is the most commonly mutated Ras family member (15~20%) among the three closely related classical Ras proteins." (PMID 26993606, 2016). "Although NRAS is currently not considered a direct target of imatinib, a recent study showed that melanoma patients with NRAS mutations are resistant to imatinib therapy." (PMID 27667448, 2016). "This described phenomenon is also found with MEK inhibitors in MAPK-driven melanoma with KIT or NRAS mutations." (PMID 27250023, 2016). "Some of the most commonly observed oncogenic events in melanoma are activating mutations of the oncogenic neuroblastoma RAS viral oncogene homolog (NRAS; typically NRASQ61K/R), which occur in 20% of cases." (PMID 27608486, 2016). "In vitro studies demonstrate that ERβ agonists can impair melanoma cell proliferation, but this depends on the genetic mutational status (NRAS vs. BRAF) of melanoma cells." (PMID 27833586, 2016). "MiR-146a (another miR-146 family member) was highly up-regulated by oncogenic BRAF and NRAS mutations in melanomas." (PMID 26646588, 2016). "Activating mutations in BRAF, present and in up to 70% of all melanomas along with NRas mutations (present in approximately 15–20% of melanomas), result in constitutive activation of MAPK signaling, promoting growth, survival, and chemoresistance." (PMID 27882308, 2016). "Using logistical modeling, the expected odds ratio of NRAS mutations in melanomas in the South Island was 2.35 times that of the North Island with a 95% confidence interval ([1.50, 3.70], P=0.00016)." (PMID 27191502, 2016). "These include not only the ~50% of BRAF mutations, but also >25% NRAS mutations and ~14% of melanomas with mutations in the RAS suppressor NF1." (PMID 27200346, 2016). "In contrast, hypoxic NRAS-(Q61L)-mutant MelJuso melanoma cells were greatly susceptible to 3-BrPA or Prima-1, but were not protected by NAC." (PMID 27863474, 2016). "NRAS mutations are found in various cancers including melanoma (20–25%), lung cancer (1%), acute myeloid leukemia (10%) and cutaneous T-cell lymphoma patients (4%)." (PMID 26821351, 2016).